TNF (tumor necrosis factor)
Diseases named in the same sentence as TNF in open-access papers (continued):
Sharing a sentence is not in itself a finding about the gene and the disease.
Tinnitus (continued). "On the other hand, dietary supplementation with C-PC or Spirulina platensis water extract significantly reduced the salicylate-induced tinnitus and down-regulated the mRNAs expression of NR2B, TNF-α, IL-1β mRNAs, and COX-2 genes in the cochlea and IC of mice." (PMID 23533584, 2013). "However, TNF-α mRNA levels were significantly decreased in the cochlea (1.3±0.1 versus 1.9±0.2, p<0.001) and IC (1.4±0.2 versus 2.1±0.2, p<0.001) of the Spirulina group and C-PC group (cochlea: 1.0±0.1 versus 1.9±0.2, p<0.001; IC: 1.0±0.1 versus 2.1±0.2, p<0.001), compared with the tinnitus group." (PMID 23533584, 2013). "Interestingly, IL-10 levels increased with the chronicization of tinnitus, while levels of IL-1α, IL-1β, IL-2, IFN-γ, TNF-α, and Transforming Growth Factor (TGF)-β remained unchanged." (PMID 40697272, 2025). "After matching, 136 (1.3%) of the No-TNFα cohort and 173 (1.7%) patients in the Yes-TNFα cohort were diagnosed with tinnitus during the study period; the mean time to tinnitus diagnosis from index was 1053.7 (SD: 782.0) and 1179.9 (952.6) days, respectively." (PMID 36902722, 2023). "In chronic tinnitus sufferers, a relaxation training program can result in significantly decreased stress, anxious depression, anger, and tinnitus disturbance, paralleled by a reduction of TNF-a, but not IL-6 or IL-10." (PMID 38027533, 2023). "Patients with autoimmune conditions without tinnitus were evaluated for rates of tinnitus development, comparing those who did and did not receive anti-TNF-α therapy." (PMID 36902722, 2023). "Specifically, compared with patients not treated with anti-TNFα, the hdPS-adjusted HR for incident tinnitus among those treated with anti-TNFα was 1.15 (0.92, 1.44)." (PMID 36902722, 2023). "In contrast with the experimental studies, there was no increase in TNF-α present in humans with tinnitus." (PMID 35207270, 2022). "While we observed correlations of IL-1b, TNF-α, and IGF-1 with tinnitus loudness, these associations did not persist in network analysis." (PMID 35814090, 2022). "The expression levels of NR2B, tumor necrosis factor-α (TNF-α) and interleukine-1β (IL-1β) genes increased significantly, whereas cyclooxygenase type 2 (COX-2) gene expression decreased in the cochlea and IC of mice with salicylate-induced tinnitus." (PMID 27590453, 2016). "In this study, we aim to investigated whether C-PC or spirulina platensis water extract could reduce the tinnitus score and expression levels of NR2B, TNF-α, IL-1β, and COX-2 genes in the cochlea and IC in response to intraperitoneal injections of salicylate." (PMID 23533584, 2013). "Therefore, we suggested that the beneficial effects of spirulina or C-PC on tinnitus mainly via inhibiting mRNA expression of NR2B, TNF-α, IL-1β, and/or COX-2 genes." (PMID 23533584, 2013). "Post-hoc analysis showed that, compared to the control group, the tinnitus group had not significantly increased TNF-α protein levels in the IC (1.51±0.19 versus 1.20±0.02, p = 0.085)." (PMID 23533584, 2013). "This experimental study showed that the both of spirulina platensis water extract and its active component (C-PC) could reduce salicylate-induced tinnitus and reduce expression of NR2B, TNF-α, IL-1β, and COX-2 genes in the cochlea and IC." (PMID 23533584, 2013). "In chronic tinnitus sufferers, a relaxation training program can result in significantly decreased stress, anxious depression, anger, and tinnitus disturbance, paralleled by a reduction of TNF-α, but not IL-6 or IL-10." (PMID 21477330, 2011). "Thus, one area of further study in the treatment of tinnitus could be to modulate the microbiome to increase GABA and dopamine and decrease TNF-alpha." (PMID 37887847, 2023). "The lack of consistent results regarding TNF-α in the present study may have been influenced by the small sample size and the generally low levels of tinnitus-related distress and psychological symptoms in our sample." (PMID 35814090, 2022).
Tinnitus (continued). "Last, damage because of the tinnitus induction methods in animals itself could be responsible for an increase in TNF-α, independent of the occurrence of tinnitus." (PMID 35207270, 2022). "To determine whether the absence of noise-induced tinnitus in TNF-α knockout mice was due to the lack of TNF-α or secondary developmental abnormalities, we infused recombinant TNF-α into the right AI of normal-hearing wild-type and TNF-α knockout mice." (PMID 31211773, 2019). "Similarly, unlike the findings in another study on salicylate-induced tinnitus, SP did not alter the gene expression of TNF-α in the cochlea or brainstem in SAMP8 mice during normal aging in this study." (PMID 28636628, 2017). "Thus, not all emergent tinnitus may be related to neuroinflammation or TNFα-mediated pathogenesis, particularly in an older cohort at risk of presbycusis." (PMID 36902722, 2023). "The core components of Liuwei Dihuang Pill in the treatment of tinnitus including quercetin, stigmasterol, kaempferol, β-sitosterol, tetrahydroalstonine, which may act on core targets such as STAT3, transcription factor AP-1 (JUN), tumor necrosis factor (TNF), interleukin-6 and MAPK3." (PMID 36401375, 2022). "Therefore, the aim of the present study is to evaluate whether the incidence of tinnitus among individuals with autoimmune conditions for which anti-TNFα are indicated differs between those who were and were not treated with anti-TNFα therapy, using a US electronic health records (EHR) database." (PMID 36902722, 2023). "Changes in the gene expressions for tumor necrosis factor-α (TNF-α) and/or interleukin-1β (IL-1β) during tinnitus have not been previously reported." (PMID 21477330, 2011).
unstable angina (38 papers, 2007 to 2025). "In this manner, the results suggest that the (rs1800629) − 308 A allelic variant was accompanied by changes TNF-alpha production and an increase in risk of angina pectoris in the Iraqi population." (PMID 36622512, 2023). "Association among plasma apoCIII, hs-CRP and TNF-α interacts with unfavorable lipid profiles to contribute to the clinical features of CHD with stable angina, unstable angina, and AMI in the Li and Han ethnic groups in China." (PMID 30053815, 2018). "Meanwhile, it could be suggested that A allele of − 308 G/A SNP of TNF-alpha is tightly correlated with a considerable risk of angina pectoris development according to the OR and the circulatory levels of TNF-alpha in the individuals with the mutant genotype." (PMID 36622512, 2023). "Taken together, these results indicate that TNF-alpha − 308 G/A polymorphism may have a significant impact on susceptibility to developing angina pectoris." (PMID 36622512, 2023). "As the results, our data observed a linked of TNF-alpha (rs1800629) − 308 G/A genetic variant with angina pectoris patients, and the A allele has been linked to the production or expression of TNF-alpha serum level and represented an etiological factor of angina pectoris." (PMID 36622512, 2023). "Patients with ACS, including those with unstable angina and acute MI, exhibit significantly elevated levels of TNF-α compared to control groups." (PMID 41511355, 2025). "On the basis of the results of this study, it was revealed as the significant increase level of the TNF-alpha in the stable and unstable angina groups as compared with control." (PMID 36622512, 2023). "Both groups were then compared in terms of connective tissue growth factor (CTGF), endothelin-1 (ET-1), tumor necrosis factor-alpha (TNF-α), and some echocardiographic indices, weekly angina attacks and nitrate consumption before and after treatment." (PMID 35538296, 2023). "The findings demonstrated a significant difference of the TNF-alpha concentration in stable and unstable angina and reached about 2-folds (86.33 ± 25.2, 95.83 ± 30.3) when compared to control group (35.98 ± 15.8) respectively." (PMID 36622512, 2023). "The results demonstrated that in the existence of the AA genotype, the concentration of TNF-alpha remained considerably higher in the examined groups, particularly in patients with unstable angina (106 ± 15.7)." (PMID 36622512, 2023). "Patients with stable angina have significantly higher levels of cytokines, such as IL-6 and TNF-α, than do patients with normal coronary arteries." (PMID 34231707, 2021). "We did observe a significantly lower concentration of both IL-6 and TNF-α in the healthy controls compared to the patients with stable angina (p = 0.001 and p = 0.03, respectively)." (PMID 23091596, 2012). "Additionally, the TNF‐α:IL‐10 ratio was notably higher in patients with unstable angina compared to control patients." (PMID 39801756, 2025). "Overall, the TNF level marked at 48 h after the cardiovascular episode has a sensitivity of 78% and a specificity of 72.5% in predicting a cardiovascular ischemic event such as angina, reinfarction, HF and death." (PMID 38396488, 2024). "The purpose of this study in order to suggest that the (rs1800629) − 308 G/A TNF-alpha allelic type might be indicator to angina pectoris." (PMID 36622512, 2023). "The results of our study indicate that the associations of plasma apoCIII, hs-CRP and TNF-α interact with unfavorable lipid profiles to contribute to the clinical features of CHD with stable angina, unstable angina, and AMI in both the Li and Han ethnic groups in China." (PMID 30053815, 2018). "The TMZ group had lower mean ± SD levels for TNF-α and CTGF and showed significant improvement in echocardiographic indices and weekly angina attacks after treatment." (PMID 35538296, 2023).
unstable angina (continued). "Among the particularly excellent compounds for unstable angina, liquiritin (MOL004903) reduces mRNA expression of TNFα, IL-6, and IL-1β, inhibits inflammatory cell migration, suppresses oxidative stress and apoptosis in the heart, and improves metabolism." (PMID 35140797, 2022). "The highest apoCIII, hs-CRP and TNF-α levels were detected in the CHD patient subgroups with AMI, followed by those with unstable angina and then those with stable angina." (PMID 30053815, 2018). "In control group, the TNFα level at day 12 and the rate of CHF class II and higher (R = 0.4; p = 0.03) directly correlated with the development of unstable angina (R = 0.5; p = 0.03)." (PMID 28558042, 2017). "Also peripheral blood mononuclear cells cocultured with TNF-α showed downregulation of the CD28 costimulatory receptor, and high levels of TNF-α are associated with higher levels of CD4+CD28− T cells in patients with unstable angina, supporting the findings of the in vitro studies." (PMID 25834833, 2015). "Secondary outcome parameters: other circulating inflammatory markers (including IL-6, TNFα, VCAM-1, CD40, sCD40L, MCP-1, and MMP-9), improvement in symptoms of angina and blood stasis syndrome, and safety." (PMID 23983803, 2013). "These cells, expanded in patients with unstable angina and infrequent in those with stable angina, produce high levels of IFN-γ and TNF-α." (PMID 23304078, 2012). "To date, there were no data on the correlation of the TNF-alpha − 308 G/A with angina pectoris in the Iraqi population." (PMID 36622512, 2023). "Bao Xin decoction (another formula to treat PSCS with IHD) was effective in curing CAD with stable angina pectoris and acting by inhibiting serum interleukin 6 (IL-6), intercellular adhesion molecule 1 (ICAM-1) and tumor necrosis factor-α (TNF-α) levels and decreasing inflammatory reactions." (PMID 29403392, 2018). "Exogenous IL‐10 significantly reduced TNF‐α and MMP9 levels in peripheral blood mononuclear cells of patients with unstable angina, suggesting that a decreased serum level of IL‐10 could be a marker of plaque instability and predict a poor prognosis after an acute ischemic event." (PMID 39801756, 2025). "In this study, there was no significant variation in the inflammatory markers (TNF-α and hs-CRP) in the subgroups of CHD with severe, moderate, and mild stenosis, while there were marked differences between each pair of subgroups of CHD patients with AMI, unstable angina and stable angina." (PMID 30053815, 2018).
viral hepatitis (38 papers, 2005 to 2025). An acute or chronic inflammation of the liver parenchyma caused by viruses. "One possible cause is the activation of the immune response and the release of cytokines associated with viral hepatitis, such as interleukin-6, interleukin-1β, and tumor necrosis factor-alpha." (PMID 37829687, 2023). "TNF-α has been implicated in the pathogenesis of viral hepatitis and is associated with inflammation and fibrotic changes in hepatocytes." (PMID 35469194, 2022). "Tumor necrosis factor-alpha and transforming growth factor-β have been implicated in the bone injury during viral hepatitis." (PMID 27398385, 2013). "In experimental cytokine-induced fetal loss or viral hepatitis, TNF-α was demonstrated to promote fgl2 expression in endothelial cells of trophoblasts and decidua or in hepatic endothelial cells." (PMID 23554679, 2011). "Neoangiogenesis in the liver of HBV-infected patients suggests that TNF-α might also have a role in the development of viral hepatitis-associated liver tumors." (PMID 23133749, 2012). "Therefore, it would not be unreasonable to believe that HSV reactivation could cause viral hepatitis in a patient on a TNFα inhibitor." (PMID 27818806, 2016). "A comparable mechanism to explain the liver involvement in viral hepatitis has been suggested by the recognized relationship between hepatic inflammation and the rise of IL-1β, TNF-α, and IL-6." (PMID 38983633, 2024). "The number of TB and viral hepatitis cases/1,000 TNFα-inhibitor patients were evaluated, and regional variation compared." (PMID 36744250, 2023). "Several studies analysed molecular and immunological mechanisms of TNF signalling during viral hepatitis in mouse infection models." (PMID 35122118, 2022). "It is well known that TNF-α is involved with liver inflammation and hepatocytes injury and mediates viral hepatitis complications." (PMID 33435966, 2021). "During fulminant viral hepatitis, a cytokine burst arises, resulting in an enrichment of the hepatic microenvironment in death factors such as TNF-α, Fas ligand (FasL) or TRAIL." (PMID 30622241, 2019). "TNF-α is a key cytokine involved in both acute and chronic liver diseases, like fulminant hepatic failure, alcohol-induced hepatitis, viral hepatitis, metabolic toxicity, drug-induced liver injury and autoimmune hepatitis." (PMID 30622241, 2019). "According to a previous study, the hepatoprotective effect of glycyrrhizin in viral hepatitis patients is due to its cytoprotective effect via the suppression of TNF-α-induced cytotoxicity and inhibition of immune-mediated cytotoxicity against hepatocytes." (PMID 23771023, 2013). "In the liver, TNF-α is involved in pathophysiology of viral hepatitis, alcoholic liver disease, nonalcoholic fatty liver disease and ischemia-reperfusion (I/R) injury." (PMID 23133749, 2012). "A high level of LPS can promote the secretion of inflammatory cytokines including TNF and interleukin-6 (IL-6), stimulating immune cells and finally may lead to the progression of viral hepatitis." (PMID 37342245, 2023). "TNF signaling promotes hepatocyte apoptosis in the liver, resulting in liver injury and indirectly contributing to carcinogenesis through a variety of inflammatory processes such as chronic viral hepatitis." (PMID 35628212, 2022). "Furthermore, cross-presenting nonprofessional APC, such as liver sinusoidal endothelial cells, can drive CD8+ T-cell TNFα production during viral hepatitis." (PMID 25121482, 2014). "However, blockade of TNF during viral hepatitis might be contraindicated not only because of the well-documented side effects of reactivation of quiescent infections but also because of restricted elimination of infected hepatocytes." (PMID 35122118, 2022).
viral hepatitis (continued). "Although there might exist virus-specific differences between LCMV and HBV infection regarding TNF-mediated exhaustion of helper and effector T cells, future studies are needed to elucidate the role of TNF and its receptors for T cell exhaustion during viral hepatitis." (PMID 35122118, 2022). "Fas, TNF-α and TRAIL are important genes in the death receptor-mediated apoptosis signaling pathway in human acute viral hepatitis, and caspase-8 is a key gene involved in this pathway." (PMID 22266786, 2012). "Certain infections, including Helicobacter pylori and chronic viral hepatitis, elicit a significant propensity for the evolution of the thyroid nodules, possibly through the upregulation of specific mediators, including CXCL10 and tumor necrosis factor-α in the thyroid gland." (PMID 38068463, 2023). "However, in our model neither TNF blockade nor FASL blockade changed the cause of fulminant viral hepatitis." (PMID 30442932, 2018). "Overactivation involving mediators such as Fas, TNF-α and TGF-β, can lead to significant acute injuries, such as fulminant hepatic failure or even chronic sustained hepatocellular damage, as occurs with toxic liver injury, viral hepatitis, alcoholic and non-alcoholic liver disease." (PMID 24714963, 2014).